IL37 (interleukin 37)
Diseases named in the same sentence as IL37 in open-access papers (continued):
Sharing a sentence is not in itself a finding about the gene and the disease.
infection (continued). "The IL-37 precursor was administered intraperitoneally once either 96, 48 or 1 hour before intranasal infection with live A. fumigatus conidia." (PMID 25375146, 2014). "Cftr−/− mice were pretreated with 1000 ng/mouse IL-37 one h before the infection and parameters of infection and inflammation were evaluated one day after the infection." (PMID 25375146, 2014). "We observed that IL-37 limits inflammation and disease severity in murine invasive aspergillosis, an infection model in which cytokines of the IL-1 family have important roles." (PMID 25375146, 2014). "Recombinant human IL-37 was injected intraperitoneally into mice prior to infection and the effects on lung inflammation and inflammasome activation were evaluated." (PMID 25375146, 2014). "Of interest, IL-37 was also effective in dampening inflammation when administered after the infection." (PMID 25375146, 2014). "Similarly, after BF.7 infection of M1 macrophages, the administration of IL‐37 led to an approximately 21% decrease in Ccl4 mRNA expression and an approximately 15% reduction in Ccl3 mRNA expression." (PMID 40452816, 2025). "Furthermore, we differentiated mouse BM‐derived cells into M1 macrophages in vitro and introduced an NF‐κB activator or inhibitor to further elucidate the mechanism by which IL‐37 affects M1 macrophages during SARS‐CoV‐2 Omicron infection." (PMID 40452816, 2025). "IL‐37 mitigates the infiltration of macrophages and suppresses the production of macrophage‐associated chemokines (such as CCL3 and CCL4) induced by SARS‐CoV‐2 Omicron infection through NF‐κB signaling pathway." (PMID 40452816, 2025). "Additionally, an in vivo study on Miana demonstrated an anti-inflammatory impact following infection of bacteria as well as a reduction in the levels of IL37, VEGF, HIF-1, and Intracellular Adhesion Molecule-1 (ICAM-1)." (PMID 38058621, 2023). "Such an early effect might be due to the fading of IL-37 pretreatment, or the acute infection was rapidly controlled by the host immunity in the liver." (PMID 37215069, 2023). "Notably, IL-37 has recently been identified to have dual effectiveness in host protection against infection." (PMID 35836813, 2022). "Anti-inflammatory cytokines, such as IL1-Ra, IL-37 or IL-38 could potentially provide relief in both systemic inflammation and fever occurring after infection." (PMID 32256705, 2020). "However, an increase in the percentage of macrophages, which were identified as CD45+F4/80+CD11b+ cells, was observed in the lungs of mice in the IL-37 administration group, peaking at day 6 post infection." (PMID 31736917, 2019). "This could suggest that an increase in IL37 expression contributes to the control of SIV replication in the digestive tract at the acute phase of the infection, favoring a better control of the infection at the set point." (PMID 31138840, 2019). "The BAL fluid was gathered 6 days after infection or IL-37 treatment." (PMID 31736917, 2019). "Moreover, IL-37 protein secreted in the supernatants of THP-1 cells markedly increased post infection with H37Rv for 24 h at indicated MOI." (PMID 28076390, 2017). "We found that IL-37 was highly presented in the lung at all time points examined in the transgenic mice but not the WT mice, and an elevated IL-37 abundance was observed as early as 1 week post infection." (PMID 28076390, 2017). "Accordingly, IL-37 was effective when administered 96 or 48 hours before the infection." (PMID 25375146, 2014). "Therefore, the presence of IL-37 in the early stages of infection results in an impaired innate immune response that is essential to limit fungal dissemination." (PMID 25620965, 2014). "Since the ROSA26 promoter drives gene expression constitutively and ubiquitously, the increased IL-37 in the lung of transgenic mice post infection could be due to increased frequencies and numbers of cells expressing IL-37 including macrophages, dendritic cells and regulatory T cells." (PMID 28076390, 2017).
infection (continued). "On one side, IL-37 may control the exacerbated inflammation by downregulating the production of proinflammatory cytokines as well as reducing Th17 cell response, which thereby protect the host from excessive tissue damage at the site of infection." (PMID 28076390, 2017). "Thus, IL-37 functions as a broad spectrum inhibitor of infection-mediated inflammation, and could be considered to be therapeutic in reducing the pulmonary damage due to non-resolving Aspergillus infection and disease." (PMID 25375146, 2014). "It is important however, to recognize that anti-inflammatory strategies based upon IL-37 could have a negative impact on susceptibility to infections by inhibiting host defense." (PMID 25620965, 2014). "Once produced, IL-37 attenuated TLR2, TLR4 and NOD1-mediated activation and TLR-mediated IL-8 responses to H. pylori infection." (PMID 41689434, 2026). "Compared with that in the infection and oseltamivir groups, the phosphorylation of ERK1/2 and p38 MAPK was significantly reduced in the IL-37 treated RAW264.7 cell group." (PMID 31736917, 2019). "To further characterize the function of IL-37 in the process of mycobacteria infection, we infected both WT and IL-37-Tg mice with M. bovis BCG intranasally (i.n.)and then assessed bacterial burden in the lung as determined by CFUs every week after infection." (PMID 28076390, 2017). "Treatment with 1000 ng/mouse of IL-37 one h before the infection neither limited inflammatory cell recruitment nor inhibited the heightened NALP3 expression activation in these mice." (PMID 25375146, 2014). "Similarly, stimulation of M1 macrophages with an NF‐κB activator and subsequent infection with Omicron BA.5 resulted in increased production of the inflammatory factors CCL3 and CCL4; nevertheless, intervention with IL‐37 significantly attenuated the expression of these chemokines." (PMID 40452816, 2025). "(B.2.1) Endothelial cells stimulated by IL-37 expression through the secretion of inflammatory mediators, including IL-1β, TNF-α, and IFN-γ, which positively induce adhesion molecules like E-selectin, ICAM-1, VCAM- 1, and VLA-4 that allow immune cells to go to the infection site." (PMID 39308868, 2024). "For IL37 rs2723186, an association with CMV disease (p = 0.0499), for IL10 rs1800872, with graft loss or death (p = 0.0207) and for IL10 rs3024496, with infections (p = 0.0258) was observed in all patients, however did not hold true after correction for multiple testing." (PMID 33861738, 2021). "Whether and how IL-37 down-regulates the inflammation of infection, and its consequences, is not known." (PMID 25375146, 2014). "When infected mice were administered rIL-37, CPP-IgG2Fc-IL-37 or no CPP-IL-37, the ratio of M2 increased more than in the infection groups." (PMID 36002836, 2022). "Recombinant IL-37 (rIL-37), CPP-IgG2Fc-IL-37 and no CPP-IgG2Fc-IL-37 proteins were injected into S. japonicum-infected mice every 3 days for a total of 6 times from day 24 post infection onwards." (PMID 36002836, 2022).
cardiovascular diseases (15 papers, 2015 to 2025). "We also explore experimental strategies and propose that targeting interleukin-37 to modulate ferroptosis presents a promising therapeutic approach for the prevention and treatment of cardiovascular diseases." (PMID 39337246, 2024). "Even with all the IL‐37 researches done since its discovery in cardiovascular diseases, much still needs to be elucidated." (PMID 28548248, 2017). "This present review discusses the molecular mechanisms encompassing experimental models and human beings and provides the first comprehensive summary of how IL‐37 plays a protective role in cardiovascular diseases." (PMID 28548248, 2017). "An increase in IL‐37 expression has been seen in certain cell types involved with cardiovascular diseases 4, 23, which has made IL‐37 a potential target in pathogenesis." (PMID 28548248, 2017). "The other two patients who underwent thrombectomy did show increased IL-37 levels in the expected range.The role of IL-37 in cardiovascular diseases has recently surfaced." (PMID 29234571, 2017). "IL-37, known for its anti-inflammatory properties, may play a protective role in cardiovascular diseases by modulating immune responses." (PMID 39767755, 2024). "Recent studies have suggested that IL‐37 plays a role in cardiovascular diseases." (PMID 28548248, 2017). "This review aims at summarizing and discussing the role of IL‐37 in cardiovascular diseases." (PMID 28548248, 2017). "Accumulating evidence shows that IL-37 plays a critical role in cardiovascular disease." (PMID 28781417, 2017).
inflammation (9 papers, 2018 to 2025). Aberrant reaction of the microcirculation characterized by movement of fluid and leukocytes from the blood into extravascular tissues. "IL-37, in murine models of inflammatory arthritis, causes the suppression of joint inflammation through the inhibition of IL-1." (PMID 34360845, 2021). "Due to the findings in the correlation between IL-37 and liver inflammation in AHB patients, the regulatory function of exogenous IL-37 to HBV peptides-induced CD8+ T cells was then assessed in vitro." (PMID 36326182, 2023). "We also uncovered that CD organoids overexpressed IL37, an anti-inflammatory cytokine related to chronic inflammation and autoimmune diseases." (PMID 31065051, 2019). "This was also associated with a significant decrease in the concentrations of IL-10, IL-37, and PPAR-α anti-inflammatory mediators (as compared to the NC-group), uncovering serious cardiac inflammation." (PMID 40672362, 2025).
infectious disease (8 papers, 2018 to 2023). A disorder directly resulting from the presence and activity of a microbial, viral, or parasitic agent in humans. "Interleukin-37 (IL-37) is a newly identified anti-inflammatory cytokine, owning immunosuppressive activity in infectious diseases." (PMID 36326182, 2023). "Thus, IL-37 owns potent immunosuppressive activity against innate and acquired immune responses through inhibition of inflammatory mediators in cancers, autoimmune diseases, and infectious diseases." (PMID 36326182, 2023).
immune disorder (5 papers, 2017 to 2023). "IL-37, a new member of the IL-1 family, acts as a novel anti-inflammatory cytokine in various inflammatory and immune diseases." (PMID 36002836, 2022). "Both endogenous and exogenous IL-37 have been shown to ameliorate inflammation and regulate immune disorder via inhibiting the production of inflammatory mediators including IFN-γ, TNF-α, IL-6, and IL-18." (PMID 28781417, 2017). "Increased IL-37 expression suggests that it may play a potential regulatory role in the immune dysfunction of patients with IM." (PMID 37507743, 2023). "In addition, the keyword “suppression” with the largest burst strength of 5.81 started to burst from 2019 to the present, which implies that the detection of immune effects of IL-37 in a wide variety of immune disorders still remains a research hotspot in future studies." (PMID 35935954, 2022).
metabolic disorders (4 papers, 2018 to 2024). "Evidence for the correlation between circulating levels of IL–33 and IL–37 in MetS and its associated metabolic disorders in human adults is scarce." (PMID 38255771, 2024). "First, factors that were found to associate with IL-37 indicated metabolic disorders, chronic inflammation, and comorbidities of CVD." (PMID 36834391, 2023).
neurological diseases (4 papers, 2014 to 2020). "In summary, elevated levels of IL-37 in the acute systemic inflammatory disorders, as well as neurological diseases, makes it an intriguing novel cytokine with potential diagnostic, prognostic, and therapeutic roles." (PMID 29234571, 2017). "Interestingly, it has been proposed the use of IL-37 (a cytokine member of the IL-1 family with immunosuppressive and anti-inflammatory properties) in neuroinflammation to help to improve the course of many neurological diseases." (PMID 31109355, 2019).
bacterial infection (3 papers, 2018 to 2024). "Since IL-37 has been demonstrated to ameliorate intestinal inflammation and protect barrier functions, it is tempting to speculate that such protection of the intestine may contribute to the rescue of IL-37tg mice from bacterial infection in the lungs." (PMID 31061403, 2019).
coronary artery (3 papers, 2018 to 2022). "In our previous study, we observed that IL-37-treated DCs from patients with ACS were phenotypically and functionally similar to IL-37-treated DCs from normal coronary artery patients." (PMID 34471467, 2021).
dermatitis (3 papers, 2024 to 2025). An inflammatory process affecting the skin. "The pathogenesis of this dermatosis is not yet fully understood, but genetic predispositions, immune dysregulation, mediated by mast cells, IL-37 and kallikrein 5, as well as neurovascular abnormalities, Demodex spp." (PMID 40217831, 2025).
cardiac disease (2 papers, 2023). "Overall, the positive role of IL-37 on other heart diseases, i.e., HF, needs to be further elucidated." (PMID 37047468, 2023). "In this review, the pathophysiological effects of interleukins including the IL-1 family (IL-1, IL-18, IL-33, and IL-37), IL-2, IL-4, the IL-6 family (IL-6 and IL-11), IL-8, IL-10, and IL-17 on primary cell types of heart disease is elucidated." (PMID 37047468, 2023). "This review will primarily focus on the pathophysiological effects of various interleukins including the IL-1 family (IL-1, IL-18, IL-33, IL-37), IL-2, IL-4, the IL-6 family (IL-6 and IL-11), IL-8, IL-10, IL-17 on primary cells of heart disease-CMs, FBs, ECs, and immune cells." (PMID 37047468, 2023).
animal disease (1 paper, 2018). "Several studies indicated that the IL-37-expressing cells have a systemic or local anti-inflammation effect in different animal disease models." (PMID 30563054, 2018).
neurodegenerative disease (1 paper, 2022). A disorder of the central nervous system characterized by gradual and progressive loss of neural tissue and neurologic function. "In this study, we showed that IL-37, an anti-inflammatory cytokine, is able to reduce both acute and chronic neuroinflammation and that the IL-37tg mouse model is a valuable animal model to study the details of neurodegenerative diseases caused by chronic inflammation." (PMID 36040311, 2022). "In general, the putative mechanism of IL-37 signaling in neurodegenerative diseases is not clear." (PMID 36040311, 2022).
renal disease (1 paper, 2014). "IL-37 associated with SLE disease activity, especially related with SLE renal disease activity." (PMID 24629023, 2014). "Serum IL-37 levels were higher in SLE patients with renal involvement compared with those without renal disease." (PMID 24629023, 2014). "Surprisingly, serum IL-37 levels were significantly higher in patients with renal disease compared with patients without renal involvement together with healthy controls." (PMID 24629023, 2014).
respiratory diseases (1 paper, 2025). "In conclusion, IL-37 is not only a critical immunoregulatory factor but also a promising diagnostic tool and therapeutic target in the field of respiratory diseases." (PMID 41293155, 2025). "The expression level of IL-37 is closely associated with the severity of respiratory diseases, indicating its potential as a biomarker for diagnosis and prognostic evaluation." (PMID 41293155, 2025). "In summary, accumulating evidence suggests that aberrant levels of Interleukin-37 (IL-37) are extensively involved in the pathogenesis of various respiratory diseases." (PMID 41293155, 2025). "Collectively, these findings demonstrate that IL-37 serves as a crucial immunomodulator in respiratory diseases, and targeting IL-37 offers novel insights and strategic opportunities for clinical intervention." (PMID 41293155, 2025). "As an anti-inflammatory cytokine with immunomodulatory functions, IL-37 demonstrates broad application prospects in the treatment of respiratory disorders." (PMID 41293155, 2025). "This review highlights the significance of IL-37 in common respiratory diseases." (PMID 41293155, 2025). "Furthermore, the advancement of IL-37 research in respiratory diseases was assessed." (PMID 41293155, 2025).
retinopathy (1 paper, 2017). "As expected, intraperitoneal administration of ALK1 inhibitor also suppressed IL-37 induced upregulation of retinopathy." (PMID 28733640, 2017). "We further show that TGF-β and ALK1 are required in IL-37 induced pro-angiogenic response in ECs and in the mouse model of Matrigel plug and oxygen-induced retinopathy." (PMID 28733640, 2017). "In mice, IL-37 enhanced angiogenesis in Matrigel plug assay and promoted neovascularization in oxygen-induced retinopathy and in neonatal retinal vasculature." (PMID 28733640, 2017).
IL37 also shares sentences with these, for which no sentence is quoted: ulcerative colitis (10 papers); chronic periodontitis (6); acute myocardial infarction (4); Allergy (4); Spondyloarthritis (4); diabetic cardiomyopathy (3); Hashimoto thyroiditis (3); acute pancreatitis (2); acute respiratory distress syndrome (2); autoimmune thyroid disease (2); Central Nervous System Diseases (2); chronic hepatitis C virus infection (2); colon (2); contact dermatitis (2); diabetic nephropathy (2); eczema (2); generalized pustular psoriasis (2); intervertebral disc degeneration (2); Listeria infection (2); lupus nephritis (2); Oral leukoplakia (2); renal carcinoma (2); Thrombocytopenia (2); Acute hepatitis (1); acute hepatitis B (1); aggressive periodontitis (1); airway hyperresponsiveness (1); alopecia areata (1); anemia (1); Anxiety (1).
A further 91 diseases each share a sentence with IL37 in 1 paper.